CXCL12 (C-X-C motif chemokine ligand 12)
Diseases named in the same sentence as CXCL12 in open-access papers (continued):
Sharing a sentence is not in itself a finding about the gene and the disease.
tumor (continued). "Adhesion molecules were identified as key proteins in relation to tumor cell invasion, and CXCL12 could also upregulate the expression of adhesion molecules such as VLA-4." (PMID 36569343, 2022). "Moreover, genetic deletion of fibroblast-specific CXCL12 significantly reduced vessel permeability compared to CXCL12 secreting CAFs within the recapitulated tumor microenvironment (TME)." (PMID 36118583, 2022). "Interestingly, the majority of tumor cells tested (4 out of 5) showed increased toxin-induced cell death in the presence of either CXCL12 or CXCL11." (PMID 36539774, 2022). "CTCE-9908 inhibits tumor cell invasion and tumor angiogenesis via the CXCL12/CXCR4 axis." (PMID 35893797, 2022). "Studies found that targeting CXCL12/CXCR4 signaling by an OV expressing CXCR4 antagonist effectively disrupted the tumor vasculature, induced ICD of cancer cells, reversed immunosuppressive TME and improved antitumor immunity, including inhibition of cancer metastasis." (PMID 36221123, 2022). "Thus, the upregulation of CXCR3 and downregulation of CXCL12 serve as exit signals, driving NK cells out of the bone marrow, resulting in an impaired anti-tumor response." (PMID 35399952, 2022). "Inhibition of the CXCL12/CXCR4 axis through the CXCR4 inhibitor plerixafor could abrogate the initial establishment of tumor growth in vivo." (PMID 36254250, 2022). "Moreover, the detrimental effect of CXCL12/CXCR4 is found to depend on the density of tumor-infiltrating CD8-positive T lymphocytes." (PMID 36612163, 2022). "While Liu’s report showed that SNHG17 could ptomote the metastasis of CRC via sponging miR-23a-3p, inducing an upregulated expression of CXCL12, a molecule which could regulate tumor angiogenesis." (PMID 35248073, 2022). "Furthermore, tumor PCs increase the expression of CX43 in MSCs leading to an increased levels of CXCL12 and stimulation of its corresponding receptor expressed on MM cells." (PMID 35064098, 2022). "Indeed, the CXCR4-mediated proliferation and metastasis of tumor cells was shown to be regulated by CXCR7 through its scavenging of CXCL12." (PMID 35406450, 2022). "Tumor expressing CXCL12 can also promote pDCs expressing CXCR4 in the tumor microenvironment." (PMID 35884612, 2022). "Tumor conditioned medium could upregulate CXCL12 expression that facilitated the migration of human BM-MSCs to tumor sites by activating JAK2/STAT3 and MEK/ERK1/2 pathways." (PMID 36324128, 2022). "IL-1β secreted by tumor-activated monocytes promoted the development of IL-17–producing CD8+ T-cell (Tc17) populations and the supernatants induced the production of the chemokine CXCL12 by tumor cells and led to functional impairment of antitumor CD8+ cytotoxic T-cells." (PMID 35382168, 2022). "Immunohistochemical analysis of human liver show that the sinusoidal endothelial cells lining the hepatic vessel wall abundantly express the CXCL12 protein, which is therefore perfectly positioned to interact with circulating tumor cells for the formation of metastases." (PMID 35406582, 2022). "Since CXCL12 could enhance tumor cell migration and invasion, we believe that tumor cells' ability of the migration and invasion was partially due to increased expression of CXCL12 by HBMECs under hypoxia." (PMID 34093792, 2021). "A small sample of tumor culture medium was supplemented with soluble CXCL12 at a concentration of 100 nM to enhance immune cell migration and some CD276-CAR NK-92 cells were pre-treated with prostaglandin E2 (PGE2) at a concentration of 5.7 μM in order to block migration." (PMID 33925968, 2021). "Expression of CXCL12 receptors on immune-system cells may be indicative of CXCL12’s role as an important soluble factor operating on effector cells in inflammatory situations and the tumor microenvironment." (PMID 34174813, 2021).
tumor (continued). "BM localization of the more functional NK KLRG1− subtypes is impaired in MM by altering the chemokine microenvironment (increasing chemokine [CXC] ligand 9 [CXCL9] and CXCL10 and reducing CXCL12 expression in BM) in a mouse tumor model of an early cancer growth stage." (PMID 34025641, 2021). "Additionally, CXCR4/CXCL12 are responsible for the homing of endothelial progenitor cells to the tumor bed and thus for initiating vasculogenesis." (PMID 34203660, 2021). "The CXCL12/CXCR4 axis plays a leading role in the CLL cell-tumor microenvironment interactions." (PMID 34207596, 2021). "Furthermore, the activated TAFs produce factors including CXCL12 to limit the T cell recruitment to tumor lesions." (PMID 34138315, 2021). "Additionally, extracellular CXCL12 promotes tumor angiogenesis through the production of VEGF-A by tumor cells." (PMID 34764346, 2021). "iCAFs express higher levels of CXCL12 compared to myCAFs, suggesting that iCAFs may play a more prominent role in preventing T cells from entering the tumor nests." (PMID 34203869, 2021). "The previous study indicated that FL cells having cancer stem cell-like activities interacted with FDCs in a CXCL12/CXCR4 dependent manner, including resistance to cyclophosphamide or doxorubicin, in vitro and in NOD/Scid mice and that a specific CXCL12/CXCR4 inhibitor exhibited tumor growth." (PMID 34069564, 2021). "Nonetheless, since an increased frequency of CD8+ cytotoxic T cells can abrogate the AOM/DSS‐induced tumor growth, we wondered whether a reduction of CXCL12 levels from senescent tumor cells can augment the effect of ICI or inhibit tumor growth directly." (PMID 33643790, 2021). "Moreover, inhibition of the CXCL12/CXCR4 signaling axis with AMD3100 (a CXCL12/CXCR4 antagonist) weakened the tumor’s mesenchymal signature in the SVZ and increased the tumor’s sensitivity to radiotherapy." (PMID 34359668, 2021). "T-cell exclusion could be mediated by fugetaxis—an active movement of T cells away from a high concentration of CXCL12 coating the tumor cells —or T-cell apoptosis similar to that observed by the engagement of CXCR4 with the gp120 coat protein of HIV." (PMID 35008248, 2021). "Blocking the CXCL12/CXCR4 signaling axis may inhibit tumor growth and provide new ideas for immunotherapy." (PMID 33894748, 2021). "Several studies have shown that the CXCR4/CXCL12 interaction may foster local tumor growth and metastatic potential by maintaining an immune-quiescent microenvironment, which could be blocked by CXCR4 antagonism." (PMID 34722241, 2021). "An increase in the expression of CXCL12 in the brain after exposure to X-ray radiation may affect the implanted tumor cells, leading to an increase in the expression of CXCR4 in tumor cells." (PMID 34764346, 2021). "Another approach to studying CXCL12 and its receptor CXCR4 took advantage of the fact that CXCR4 is the most commonly expressed chemokine receptor in most cancers and has been linked to tumor spread and poor prognosis." (PMID 34833360, 2021). "Furthermore, in a subcutaneous mouse model of PDAC, CXCR4 blockade by AMD3100 reduced intratumor blood flow and tumor vascular density, supporting that CXCL12 can promote angiogenesis." (PMID 35008248, 2021). "Moreover, CD69 controls T-cell differentiation through its interaction with galectin-148, and TGF-β-triggered CXCL12/CXCR4 signaling has been demonstrated to promote tumor invasion, metastasis, and therapeutic resistance." (PMID 34001881, 2021). "The aim for the future is, to inject these CXCL12-carrying nanoparticles into a hydrogel which could be used to fill up the cavity after tumor resection, thus attracting disseminated tumor cells." (PMID 34203660, 2021). "vCAF can induce tumor progression via the secretion of CXCL12 and VEGF, which promote angiogenesis." (PMID 35008832, 2021).
tumor (continued). "Likewise, in AOM/DSS‐induced mouse CRC containing senescent tumor cells, CXCL12 neutralizing antibody induced robust CD8+ T cell infiltration into the intratumoral epithelium along with a significant reduction in the number and size of tumors." (PMID 33643790, 2021). "Therefore, the screening of antagonists targeting the CXCL12/CXCR4 signaling pathway is a promising target for tumor therapy." (PMID 34447750, 2021). "Although the role of CXCR4 is better characterized in the tumor interstitium, the CXCR4/CXCL12 axis is also expressed in the tumor vasculature where it is known to promote angiogenesis and vascularization through induction of VEGF and/or recruitment of endothelial progenitor cells." (PMID 34793563, 2021). "For example, FAP-expressing CAF have been shown to exclude T-cells from tumours through secretion of CXCL12; targeting the CXCL12/CXCR4 signalling axis using plerixafor (a CXCR4 inhibitor) has been shown to overcome this exclusion effect and promote response to anti-PD-1." (PMID 35048030, 2021). "Nonetheless, the detailed mechanisms of how CXCR4 /CXCL12 interaction stimulates metastasis and/or tumor growth and their complete implications on metastatic lung cancer in bone are unknown." (PMID 36046435, 2021). "Collectively, the results indicated that CXCL12/CXCR4 might promote PNI by provoking the tumour cell to differentiate towards Schwann‐like cell through Twist/S100A4 axis in SACC." (PMID 34170080, 2021). "Another mechanism of tumor recurrence is the resistance to TMZ treatment which could be promoted by the upregulation of FOXM1 mediated through CXCR4/CXCL12." (PMID 34203660, 2021). "Moreover, the CXCL12 produced by tumor cells attracts CXCR4+ Treg and pro-tumorigenic myeloid-derived suppressor cells, further promoting tumor progression." (PMID 33805447, 2021). "CXCL12 suppresses the anti-tumour functions in macrophages in the TME." (PMID 34885111, 2021). "However, while CXCR4/CXCL12 regulates the functions of vascular endothelial cells and tumour cells, their influence on NK cell function is still under debate." (PMID 34709764, 2021). "At the same time, a chronic hypoxia-induced increase in CXCR4 expression stimulates the proliferation of cancer cells and causes their migration and invasion, especially in combination with the chronic hypoxia-induced increase in CXCL12 expression in tumor cells." (PMID 33467722, 2021). "In addition, CXCR4 and its ligand CXCL12 have been demonstrated to facilitate the accumulation of MDSC at the tumor site in different tumor models." (PMID 33578808, 2021). "CXCL12 works synergistically with vascular endothelial growth factor to induce neovascularization by attracting endothelial progenitor cells into the tumor microenvironment, resulting in a sufficient oxygen supply for tumor maintenance." (PMID 33710803, 2021). "Methylation patterns also play an important role in CXCR4 expression, the lack of them being associated positively with tumor size, stage, lymph node status, metastasis, and CXCL12 promoter region methylation." (PMID 33530455, 2021). "Moreover, CXCR4 is presented on circulating tumor cells released from tumors into the peripheral blood, which induces their spread to CXCL12-positive distant sites." (PMID 34203877, 2021). "Analysis with TIMER showed strong correlation between NRP1 expression and the abundance of tumor progression-related genes, MMP1, MMP3, MMP9, VEGFC, FLT4 and CXCL12 in LUSC, while there isn’t clear association between NRP1 expression and this panel of pro-tumorigenic genes in LUAD." (PMID 34168096, 2021). "Thus, CXCL12 prevents tumour cell apoptosis following camptothecin or TMZ treatment, but drug sensitivity can be re-established in the presence of the ACKR3 antagonist CCX733." (PMID 33803414, 2021). "In addition, increasing evidence indicates that the CXCL12/CXCR4 axis plays an important role in the biological processes of tumor cells." (PMID 33710803, 2021).
tumor (continued). "The in-depth study of CXCL12 and iCAFs may have particular implications for the senescent tumor microenvironment." (PMID 34801033, 2021). "CXCL12 is a classic chemokine that can promote tumor cells in the bone marrow to enter dormancy." (PMID 34712663, 2021). "Next, we used tissue staining to assess the relative distribution of CXCL12 within the tumor." (PMID 33988305, 2021). "By interrupting tumour–PSC interplay via the CXCL12/CXCR4 axis, these nanoparticles induced multiple immunostimulatory effects, including CD8+ T cell recruitment and a proportional reduction in M2 macrophages, which were potentiated upon co-loading of a microRNA that restored PSC quiescence." (PMID 34944794, 2021). "Furthermore, CXCL12 activates tumor cells’ migration to target specific organs via a CXCL12-CXCR4 axis chemotactic gradient." (PMID 33390169, 2021). "BoxA suppresses tumor cell growth while, in contrast, CXCL12 promotes tumor cell growth." (PMID 33956406, 2021). "CXCL12/CXCR4 mediates the B regulatory cells recruitment to the tumor inhibiting T cell activity." (PMID 33937018, 2021). "Thus, we conclude that TNC plays an important role in regulating macrophages and CD8 TIL through CXCL12/CXCR4 signaling thereby impairing tumor cell killing and promoting tumor growth." (PMID 33988305, 2021). "Moreover, IL-6 upregulates the expression of the androgen receptor and of CXCR4 on tumor cells, thereby favoring tumor cell proliferation and recruitment to bone via the CXCL12/CXCR4 axis." (PMID 34064859, 2021). "Moreover, tumor-derived CXCL12 gradients recruit MSCs that generally promote tumor and vessels growth, protect the CSC compartment from chemotherapy and radiation, and can even differentiate into CAFs to further amplify TME signals." (PMID 33530455, 2021). "When the authors exposed human MSCs to tumor cell-conditioned medium for 30 days, markers of CAFs (such as vimentin, FSP, α-SMA, or CXCL12) increased, supporting the hypothesis of tumor cell-mediated MSC differentiation towards a protumoral CAF state." (PMID 33530455, 2021). "MSCs are also capable of inducing thermotolerance in tumor cells via the CXCL12 pathway, which may limit the effectiveness of HIPEC therapy." (PMID 33806802, 2021). "We demonstrated a differential expression of the axis components between malignancy and normal adrenal, showing a reduced expression of CXCL12 protein in the tumor compared with the normal adrenocortex, and confirming the CXCR4 and CXCR7 expression as reported in the literature." (PMID 34834449, 2021). "Instead, local use of dipeptidyl peptidase-4 (DPP4) inhibitors to block CXCL12-inactivating enzymes may be hypothesized to locally increase the ligand levels and further validate this role of this chemokine in impairing tumor progression toward metastasis." (PMID 34834449, 2021). "Moreover, increasing evidence indicates that CXCL12 can induce immune evasion by recruiting infiltrating MDSCs into the tumor microenvironment." (PMID 34911533, 2021). "Activation of the CXCR4/CXCL12 pathway is associated with the formation of an immunosuppressive tumor microenvironment, and X4P-001 (a CXCR4 antagonist) can block excessive activation of this pathway to reverse tumor immune escape." (PMID 33746989, 2021). "Furthermore, the expression of CXCR7, the receptor for both CXCL12 and CXCL11, is overexpressed in both primary tumor lesions and metastatic lymph nodes and is associated with poor EC prognosis." (PMID 33390169, 2021). "The CXCR4 expression on tumor cells is upregulated by hypoxia and by other angiogenic factors, which are capable of directing the trafficking of normal and malignant cells expressed high levels of CXCL12 and CD44 43-45." (PMID 34093792, 2021). "Thus, CXCL12 has multiple functions in tumor biology including (a) promotion of cell survival, cell invasion, and CSCs features; (b) recruitment of stromal cells to the TME to promote tumor growth and immune evasion; and (c) promotion of angiogenesis." (PMID 33530455, 2021).
tumor (continued). "Moreover, CXCL12 in the tumor microenvironment was reported to induce macrophage mobilization and vasculogenesis." (PMID 34174813, 2021). "In addition, they secrete chemoattractants such as CCL5, CXCL1, CXCL5, CXCL7 and CXCL8 and CXCL12, which induce migration of tumor cells to metastatic lesions." (PMID 34112253, 2021). "As the CXCR4/CXCL12 axis was well known for chemotaxis of tumor cells in bone metastasis, we co-cultured TNBC cell lines with reduced CTNND1 together with fibroblasts, osteoblasts and CXCL12 cytokine, respectively, as CXCL12 was mainly produced by fibroblasts and osteoblasts in bone." (PMID 34830862, 2021). "In addition, stimulation of the CXCL12/CXCR4 signaling contributes to organ colonization with blood circulating tumor cells in HCC." (PMID 34386499, 2021). "Indeed, senescent tumor cells exhibit high invasion ability and have an improved survival via CXCL12/CXCR4 signaling." (PMID 33954107, 2021). "The results showed that exogenous and autocrine IL-1α could significantly increase the secretion of CXCL12 by the important stromal fibroblasts in tumor microenvironment, which could be inhibited by interleukin 1 receptor antagonist (IL-1Ra)." (PMID 34930323, 2021). "EPCs are recruited into ischemic or hypoxic tumours predominantly in response to chemokines (e.g., CXCL12, CCL2, CCL5) and growth factors (e.g., VEGF, bFGF), which interact with their respective receptors (e.g., CXCR4, CCR2, CCR5, VEGFR2) on the surface of EPCs." (PMID 34035882, 2021). "High CXCL12 expression in CAFs significantly correlated with the histological grade (P=0.012) and TNM stage (P=0.014), while Wnt5a expression was associated significantly with primary tumor category (P=0.016)." (PMID 33854601, 2021). "The CXCL12 Hscore was similar in the different tumor subtypes." (PMID 33988305, 2021). "In addition, CXCL12 in combination with anti-PD-L1 immunotherapy has shown a synergic anti-tumor effect and is considered a potential target for those PCs with high FAP expression." (PMID 33477288, 2021). "Furthermore, the CXCL12/CXCR4 axis activates multiple signaling pathways to promote tumor cell proliferation, invasion, distant metastasis, and inhibit apoptosis." (PMID 34447750, 2021). "Furthermore, inhibition of CXCL12 from senescent tumor cells enhances T cell infiltration and results in reducing the number and size of tumors in azoxymethane (AOM)/dextran sulfate sodium (DSS)‐induced CRC." (PMID 33643790, 2021). "At the same time, CXCL12 can also promote the proliferation and survival of tumor cells." (PMID 34930323, 2021). "CXCL12 is elevated in the TME and is produced by tumor-associated fibroblasts." (PMID 33980266, 2021). "The CXCL12 chemokine could be secreted by many types of cells, including immune cells such as primary blood monocytes, macrophages, as well as tumor cells from prostate and other tissues." (PMID 33808801, 2021). "CAFs are characterized by the secretion of high amounts of collagen in the HCC stroma or ECM, and the upregulation of the chemokine CXCL12, also known as stromal-cell-derived factor 1 (SDF-1), which stimulates tumor growth and neo-angiogenesis by the recruitment of endothelial progenitor cells." (PMID 35008212, 2021). "Further exploration of the CXCL12 expression levels between patients with different clinical statuses demonstrated significantly higher CXCL12 expression in BLCA patients with higher tumor grade (p < 0.001), advanced clinical stage (p < 0.001), lymph node metastasis (p < 0.01)." (PMID 34801033, 2021). "The binding of CXCL12 to CXCR4 or ACKR3 on tumour cells has contrasting effects." (PMID 33803414, 2021).